INS (insulin)
Diseases named in the same sentence as INS in open-access papers (continued):
Sharing a sentence is not in itself a finding about the gene and the disease.
type 1 diabetes (continued). "In this high-risk group of individuals with type 1 diabetes, the adjustment of insulin therapy is often challenging, and the risk of hypoglycemia, especially nocturnal hypoglycemia, is elevated." (PMID 40932945, 2025). "Type 1 diabetes (T1D) is a chronic autoimmune condition characterized by immune-mediated destruction of pancreatic beta-cells, leading to progressive loss of insulin production that eventually requires lifelong insulin therapy for survival." (PMID 39860426, 2025). "The results clearly show that the FRNN-FO algorithm effectively captures the chaotic behavior associated with type 1 diabetes in the insulin-glucose regulatory system, surpassing other identification methods." (PMID 41345203, 2025). "Type 1 diabetes (T1D) is caused by autoimmune-mediated destruction of the pancreatic β-cells, ultimately leading to an absolute deficiency of insulin." (PMID 41567805, 2025). "The current study demonstrates that insulin pump therapy is associated with improved and sustainable glycemic control across all age groups with type 1 diabetes." (PMID 41146752, 2025). "The selective destruction of insulin-producing β cells within pancreatic islets is a hallmark of type 1 diabetes, which requires patients to take daily exogenous insulin to maintain normal blood glucose levels." (PMID 39936941, 2025). "The insulin sensitivity levels of individuals with type 1 diabetes are influenced by the PPARG and TCF7L2 polymorphisms." (PMID 40225541, 2025). "Type 1 diabetes (T1D) is caused by immune-mediated loss of insulin-producing β cells in pancreatic islets." (PMID 41299435, 2025). "In adults with type 1 diabetes from different areas of Italy, real-life use of advanced technologies for glucose monitoring and/or insulin delivery, particularly HCL/AHCL systems, is associated with improved glucose metrics and device satisfaction." (PMID 39387915, 2025). "Type 1 diabetes mellitus (T1D) is a long-term autoimmune condition that involves the destruction of beta cells in the pancreas that produce insulin, resulting in insulin deficiency." (PMID 39852829, 2025). "Type 1 Diabetes (T1D) is caused by immune-mediated destruction of pancreatic beta cells, which produce insulin." (PMID 39510129, 2025). "Their roles mostly center on immunological control, cellular apoptosis, and stress responses; processes which are linked to the autoimmune destruction of insulin-producing beta-cells in the pancreas that is a hallmark of type 1 diabetes." (PMID 41361288, 2025). "In patients with known type 1 diabetes, the most common provoking factors were inadequate insulin therapy and infection related causes." (PMID 40940823, 2025). "Secondly, Type 1 diabetes is an autoimmune disease caused by the immune-mediated destruction of insulin-producing pancreatic β cells." (PMID 40242243, 2025). "Type 1 diabetes leads to a deficiency in the body’s own production of the hormone insulin, meaning that injections of insulin are vital to regulate glucose metabolism." (PMID 40255682, 2025). "A previously published randomized clinical trial showed that, compared to a portion-controlled diet, a vegan diet resulted in a clinically significant weight loss and improvements in insulin sensitivity in adults with type 1 diabetes." (PMID 40474900, 2025). "In type 1 diabetes (T1D), the loss of insulin-producing beta-cells is the hallmark pathophysiological alteration." (PMID 40650727, 2025). "Type 1 diabetes (T1D) is caused by the autoimmune destruction of pancreatic β−cells, creating a lifelong need for exogenous insulin and glucose monitoring." (PMID 41244048, 2025). "In contrast, type 1 diabetes (T1D) typically presents early in life, resulting from the autoimmune destruction of pancreatic beta cells and absolute deficiency of endogenous insulin production." (PMID 41200383, 2025).
type 1 diabetes (continued). "Type 1 diabetes is typically characterized by autoimmune destruction of pancreatic β cells, resulting from the immune system attacking insulin-producing cells, and is associated with both genetic and environmental factors." (PMID 38780218, 2024). "Type 1 diabetes (T1D) is caused by immune-mediated destruction of insulin-secreting β cells in the pancreas, and in vivo inhibition of eIF5AHyp by GC7 treatment has been shown to delay the onset of T1D in a humanized mouse model of T1D." (PMID 39125743, 2024). ",22, 23, 24 In type 1 diabetes-prone mouse models, nicotine-induced immunosuppression is linked to preserved insulin content and lower incidence of the disease." (PMID 38019976, 2024). "Type 1 diabetes (T1D) is an autoimmune disease initiated by genetic predisposition and environmental influences, which result in the specific destruction of insulin‐producing pancreatic β‐cells." (PMID 38129973, 2024). "The cost associated with type 1 diabetes care is considerable and the rising price of insulin has further amplified this financial burden." (PMID 39087202, 2024). "In type 1 diabetes (T1D), autoantigens include citrullinated β-cell antigens, insulin peptides covalently cross-linked to other peptides by transglutaminase, and peptides from abnormally spliced transcripts." (PMID 38994353, 2024). "A previous GWAS of KET also detected several candidate genes associated with insulin metabolism and insulin-dependent diabetes." (PMID 38674346, 2024). "Type 1 diabetes is an autoimmune disorder leading to the breakdown of the beta-cells and the loss of insulin production, often diagnosed in childhood." (PMID 38606021, 2024). "Type 1 diabetes (T1D) results from the autoimmune destruction of the insulin-producing beta cells of pancreatic islets, causing high glycemia levels." (PMID 39436890, 2024). "In type 1 diabetes (T1D), these cells are targeted by auto-reactive T cells, leading to a loss of 70–90% of β-cell mass and a consequent reduction or cessation of insulin secretion." (PMID 39279997, 2024). "The autoimmune workup revealed impaired endogenous insulin production, indicated by low C-peptide levels, a condition typical in type 1 diabetes (T1D) and insulin-dependent type 2 diabetes, and associated with poorer glycemic control outcomes." (PMID 39219904, 2024). "Islet transplantation is increasingly recognized as a viable treatment for type 1 diabetes that aims to restore endogenous insulin production and mitigate complications associated with exogenous insulin dependence." (PMID 38605972, 2024). "Type 1 diabetes is caused by a deficiency of insulin secretion which has been considered traditionally as the outcome of a precipitous decline in the viability of β-cells in the islets of Langerhans, brought about by autoimmune-mediated attack." (PMID 38231086, 2024). "Type 1 diabetes is a chronic autoimmune disease associated with insulin-producing beta cell destruction, declining insulin secretion, and elevated blood glucose." (PMID 39280005, 2024). "Type 1 diabetes mellitus is marked by chronic hyperglycemia due to complete insulin deficiency, requiring lifelong insulin replacement therapy." (PMID 38435866, 2024). "In patients with type 1 diabetes (T1D), autoimmune destruction of islet β cells in the body leads to loss of insulin secretion ability, resulting in hyperglycemia." (PMID 38225568, 2024). "With the optimized multi-PTM profiling workflow, we next attempted to demonstrate its utility in profiling dynamic multi-PTM regulation in insulin-producing mouse pancreatic β-cells, the loss of which is a hallmark of type 1 diabetes." (PMID 39550035, 2024). "Type 1 diabetes (T1DM) is usually associated with insulin production failure, which is due to t cell mediated autoimmune damage to the pancreas β Cells." (PMID 38601207, 2024).
type 1 diabetes (continued). "Type 1 diabetes (T1D) is an autoimmune disease initiated by genetic predisposition and environmental influences resulting in the specific destruction of the insulin‐producing pancreatic β‐cells." (PMID 38129973, 2024). "Increased serum myostatin levels are associated with type 1 diabetes and insulin secretion deficiency." (PMID 39562792, 2024). "CFRD has features of both type 1 diabetes (T1D) and type 2 (T2D), although deficient insulin secretion and beta-cell dysfunction prevail." (PMID 39641365, 2024). "Type 1 diabetes mellitus (T1DM) is a severe auto-immune disease caused by severe destruction of insulin-producing β-cells in the pancreas, resulting in hyperglycemia." (PMID 38762484, 2024). "Type 1 diabetes (T1D) is characterized by a prolonged autoimmune attack resulting in the massive loss of insulin-producing beta cells." (PMID 39744389, 2024). "The study indicates that the mutation is associated with the synthesis of autoantibodies to insulin, which manifests itself more rapidly in children carrying high-risk HLA haplotypes or in first-degree relatives with type 1 diabetes." (PMID 38398001, 2024). "Type 1 diabetes (T1D) is a chronic metabolic disease that results from the autoimmune destruction of pancreatic beta islet cells with subsequent loss of endogenous insulin production." (PMID 39622650, 2024). "Long-term chronic hyperglycemia can be due to a deficiency in insulin production or the development of insulin resistance, which can result in type 1 diabetes mellitus (T1DM) or T2DM." (PMID 39457698, 2024). "Type I diabetes (T1D) is caused by selective destruction of insulin-producing β-cells by autoimmune attack, while the much more prevalent type II diabetes (T2D) is associated with chronic low-level inflammation and relative insulin deficiency." (PMID 38346191, 2024). "In this work, we used both insulin-deficient STZ-induced type 1 diabetes (T1D) and insulin-resistant type 2 diabetes (T2D; Lepob/ob) mouse models." (PMID 38534376, 2024). "Indicators of insulin secretion appear helpful for interpreting associations of progression to type 1 diabetes with HOMA-IR or the Matsuda Index in AAb-positive relatives." (PMID 37914981, 2024). "Type 1 diabetes mellitus (T1D) is an autoimmune disease caused by the gradual destruction of the pancreatic insulin-producing β-cells." (PMID 38397254, 2024). "Type 1 diabetes primarily involves autoimmune destruction of insulin-secreting cells, leading to insulin deficiency." (PMID 39664063, 2024). "The destruction of pancreatic beta cells leads to type 1 diabetes, resulting in decreased insulin secretion and deficiency." (PMID 39247010, 2024). "Previous research suggests that cognitive impairment is a complication of type 1 diabetes, which is associated with impaired synaptic plasticity and neuron loss due to weakened insulin action." (PMID 39203886, 2024). "Type 1 diabetes (T1D) refers to an autoimmune disease leading to the self-destruction of insulin-producing pancreatic ß cells and insulin deficiency, which leads to impaired glucose metabolism." (PMID 38892608, 2024). "Type 1 diabetes (DM1) is a metabolic disorder caused by an autoimmune reaction that leads to the destruction of insulin-secreting beta cells in the pancreas." (PMID 38956183, 2024). "Management of type 1 diabetes (T1D) requires the use of insulin, which can cause hypoglycaemia (low blood glucose levels)." (PMID 39468682, 2024). "Type 1 diabetes is an autoimmune disease that causes the destruction of the insulin-producing pancreatic β cells resulting in insulin deficiency." (PMID 39201727, 2024). "Type 1 diabetes (T1D) results from an autoimmune attack and massive loss of functional insulin-producing beta cells in the pancreas." (PMID 39744389, 2024). "Type 1 diabetes is an autoimmune disease that is caused by destruction of the insulin-secreting beta cells in the islets of Langerhans in the pancreas." (PMID 39103720, 2024).
type 1 diabetes (continued). "Type 1 diabetes causes autoimmune destruction of insulin-producing cells in the pancreas and leads to a complete deficiency of insulin, and it typically emerges in childhood with sudden onset symptoms." (PMID 38313987, 2024). "It is worth emphasizing that our findings for the STZ-induced diabetic model reinforce the need for other therapies to be used in combination with insulin treatment in the management of cardiovascular risk in patients with type 1 diabetes." (PMID 38794147, 2024). "In Type 1 diabetes, maternal cells have been implicated in either attacking the offspring’s pancreatic β-cells, producing insulin, differentiating into endocrine and exocrine cells, or serving as markers of tissue damage." (PMID 39336498, 2024). "Type 1 diabetes mellitus is a chronic disease caused by insulin deficiency following autoimmune-mediated destruction of insulin-producing pancreatic beta cells." (PMID 38030736, 2024). "In type 1 diabetes, host immune cells (i.e., T lymphocytes) attack the pancreatic beta cells and destroy the insulin-secreting pancreatic beta cells, causing the pancreas to stop insulin secretion further." (PMID 38505447, 2024). "The T cell-mediated autoimmune condition known as type 1 diabetes causes the loss of insulin-producing β cells in the pancreas." (PMID 38311623, 2024). "This cohort study examines the association of use of continuous glucose monitoring and insulin pumps with diabetic retinopathy among patients with type 1 diabetes." (PMID 38446483, 2024). "Type 1 diabetes is a chronic autoimmune condition characterized by insulin deficiency caused by the destruction of insulin-producing pancreatic β-cells." (PMID 38920672, 2024). "Type 1 diabetes (p < 0.01), time since diagnosis longer than five years (p < 0.01) and insulin treatment (p < 0.01) were positively associated with DSME participation." (PMID 39264968, 2024). "In type 1 diabetes (T1D), beta cells in pancreatic islets are selectively targeted for autoimmune destruction, leading to a marked deficiency in insulin secretion." (PMID 39003281, 2024). "Type 1 diabetes (T1D) is an autoimmune disorder characterized by the autoimmune destruction of the β cells in the pancreas, which are responsible for insulin production, and is another disorder likely linked to the dysregulation of our microbiota." (PMID 38732276, 2024). "Type 1 diabetes (T1D) is a chronic condition caused by the immune system damaging the pancreas, the organ which makes insulin, and impacts every aspect of a person’s life." (PMID 39925650, 2024). "Type 1 diabetes (T1D) is characterized by a complete insulin deficiency and required exogenous insulin administration." (PMID 39534224, 2024). "People with diabetes type 1 have abnormally high blood glucose levels because their systems are unable to manufacture insulin, a hormone that causes the condition." (PMID 37647325, 2023). "Type 1 diabetes mellitus (T1DM) is a disease caused by the autoimmune destruction of insulin-producing beta cells, which directly interferes in glucose metabolism, leading to a hyperglycemic state." (PMID 37122742, 2023). "Yet, many people with type 1 diabetes refrain from exercising, since it increases the risk for hypoglycemia and requires adjusted insulin treatment." (PMID 36791144, 2023). "Type 1 diabetes mellitus (T1D) is an autoimmune disease that arises from the selective and progressive loss of insulin-producing β cells by means of self-reactive T lymphocytes." (PMID 37373070, 2023). "Although exogenous insulin is essential for the treatment of type 1 diabetes (T1D), the association of insulin treatment with suboptimal glycemic control and an increased risk of weight gain and hypoglycemia underscores the need for adjunctive treatments." (PMID 37954838, 2023). "Type 1 diabetes is caused by the autoimmune destruction of pancreatic beta-cells, leading to a complete deficiency of insulin secretion." (PMID 38213551, 2023).
type 1 diabetes (continued). "On the other hand, in a large case-control study published in 2008 involving adults with type 1 diabetes, insulin pump treatment was associated with a significantly higher DTSQ score compared to those treated with a multi-injection regimen." (PMID 37185052, 2023). "The criteria for type 1 diabetes and disordered eating (T1DE) are type 1 diabetes, intense fear of weight gain, and inappropriate recurrent restriction of insulin causing diabetic distress and impairment of daily functioning." (PMID 37105747, 2023). "Type 1 diabetes (T1D) is a chronic autoimmune disease characterized by a loss of self-tolerance to autoantigens expressed by the insulin-producing β-cells in the pancreas." (PMID 37226224, 2023). "Type 1 diabetes usually results in near absolute loss of insulin secretion due to the autoimmune destruction of the beta-cells of the islet of Langerhans of the pancreas." (PMID 36778553, 2023). "Insulin-producing pancreatic β cell death is the fundamental cause of type 1 diabetes (T1D) and a contributing factor to type 2 diabetes (T2D)." (PMID 37015918, 2023). "Exogenous insulin therapy is the mainstay treatment for Type-1 diabetes (T1D) caused by insulin deficiency." (PMID 36845170, 2023). "Type 1 diabetes (T1D) results from the immune-mediated destruction of the insulin-producing beta cells, leading to insulin deficiency and ensuing hyperglycemia (stage 3)." (PMID 38027120, 2023). "Despite great advances in insulin formulations and medical technology devices, people living with type 1 diabetes still have an increased risk of complications and, dependent on age at diagnosis and sex, have a shortened life span by 10–18 years." (PMID 37221247, 2023). "Type-1 diabetes, an autoimmune disease characterized by damage to pancreatic insulin-producing beta cells, is associated with adverse renal, retinal, cardiovascular, and cognitive outcomes, possibly including dementia." (PMID 36901457, 2023). "“Nod” is commonly used for modeling “type 1 diabetes”, and loss of “insulin” secretion is a key mechanism for the progression of prediabetes to “type 1 diabetes”." (PMID 36908460, 2023). "Knowledge of insulin regulation of proteostasis is essential to understanding the insulin effects both in normal physiology and in pathological conditions and/or mechanisms arising from insulin-deficient conditions, such as type 1 diabetes." (PMID 38201949, 2023). "The decrease in the blood glucose level after treatment with DAPA in type 1 diabetes was often associated with a reduction in the insulin dose, which leads to an increase in the glucagon level." (PMID 36650229, 2023). "Type 1 diabetes (T1D) is an autoimmune disease characterized by T cell-mediated destruction of pancreatic β cells and absolute deficiency of insulin." (PMID 37322504, 2023). "Adolescents and young adults with type 1 diabetes, especially females and those with high body mass index, are at greater risk of disordered eating behaviors, insulin restriction, and poorer glycemic control." (PMID 36837546, 2023). "Type 1 diabetes (T1D) is a chronic, incurable, autoimmune disease caused by the T-cell mediated destruction of the pancreatic, insulin producing, beta-cells." (PMID 36619657, 2023). "An autoimmune disease known as type 1 diabetes promotes the loss of pancreatic beta cells, resulting in insufficient insulin production and hyperglycemia." (PMID 37074460, 2023). "In Type 1 Diabetes (T1D), loss of immune tolerance allows autoreactive T cells to destroy the insulin-producing beta cells in the pancreatic islets." (PMID 37346035, 2023). "In one family, the pathogenic INS p.(Gly32Ser) variant was also detected in the patient's mother and maternal grandmother who were diagnosed with ‘type 1 diabetes’ at 3 years." (PMID 36398453, 2023). "Type 1 diabetes is a chronic auto-immune condition caused when the pancreas stops making the hormone insulin, which is essential to regulating blood glucose levels." (PMID 38096018, 2023).